RAD18 (RAD18 E3 ubiquitin protein ligase)
Diseases named in the same sentence as RAD18 in open-access papers (continued):
Sharing a sentence is not in itself a finding about the gene and the disease.
hepatocellular carcinoma (4 papers, 2018 to 2024). A malignant tumor that arises from hepatocytes. "LncRNA ROR promotes radioresistance through acting as a ceRNA for microRNA145 to regulate RAD18 expression in hepatocellular carcinoma." (PMID 30406146, 2018). "Moreover, linc-ROR functioned as a molecular sink for miR-145 to regulate the lncRNA RAD18 E3 ubiquitin-protein ligase (RAD18) expression, promoting DNA repair and radioresistance in hepatocellular cancer cell lines." (PMID 36827545, 2023). "In hepatocellular cancer, lncRNA ROR upregulated radioresistance via miR-145/RAD18 axis." (PMID 35600868, 2022).
cervical cancer (3 papers, 2022 to 2025). A primary or metastatic malignant neoplasm involving the cervix. "This is the first report providing evidence for the association between the RAD18 gene polymorphism and human cervical cancer risk." (PMID 40859476, 2025). "Association between RAD18 rs250403 polymorphism and the risk for cervical carcinoma stratified by clinical pathological characteristics." (PMID 40859476, 2025). "Association between RAD18 rs615967 polymorphism and the risk for cervical carcinoma stratified by clinical pathological characteristics." (PMID 40859476, 2025). "For instance, RAD18 enhances cell migration and invasion in cervical cancer by activating the JNK‐MMPs pathway." (PMID 39865406, 2025). "With respect to cervical cancer, RAD18 stimulates the migration as well as metastasis of carcinoma cells by activating the interleukin (IL)‐1 receptor pathway." (PMID 35426246, 2022). "For instance, RAD18 can promote cervical cancer cell invasion by affecting the interleukin‐1β pathway." (PMID 35426246, 2022). "To date, there is no literature involving genetic variations of the RAD18 gene and susceptibility to cervical cancer." (PMID 40859476, 2025).
triple-negative breast carcinoma (3 papers, 2021 to 2026). An invasive breast carcinoma which is negative for expression of estrogen receptor (ER), progesterone receptor (PR), and human epidermal growth factor receptor 2 (HER2). "Herein, we performed a comprehensive pan-cancer multi-omics analysis and validated the oncogenic mechanisms of RAD18 in liver hepatocellular carcinoma, pancreatic adenocarcinoma and triple-negative breast cancer via in vitro and in vivo assays." (PMID 42115304, 2026). "Moreover, low RAD18 expression predicted a favorable response to immune checkpoint blockade therapy, while its high expression correlated with anti-PD-1 resistance in triple-negative breast cancer." (PMID 42115304, 2026). "However, the mechanism through which RAD18 influences triple-negative breast cancer (TNBC), especially the interaction between tumor cells and the tumor microenvironment, remains elusive." (PMID 35413945, 2022).
colon cancer (2 papers, 2018 to 2023). "RAD18 Arg302Gln increases the colon cancer risk in Japanese patients, while biallelic mutations in NTHL1, result in NTHL1-associated polyposis." (PMID 37738679, 2023). "Low penetrant colon cancer risk factors include polymorphisms in the DNA repair genes RAD18, ERCC5, XPC, PARP, and APE1." (PMID 37738679, 2023). "Considering that human orthologs NTHL1 and RAD18 are risk factors for colon cancer, our results provoke further studies suggesting that polymorphic NTHL1 alleles may confer HAA sensitivities." (PMID 37738679, 2023). "Alleles mapping in human orthologs RAD18 and NTHL1, increase the risk of colon cancer." (PMID 37738679, 2023).
esophageal cancer (2 papers, 2024 to 2025). A primary or metastatic malignant neoplasm involving the esophagus. "Elevated RAD18 expression is linked to tumor progression and poor prognosis in several cancers, such as cervical and esophageal cancers." (PMID 39865406, 2025).
esophageal squamous cell carcinoma (2 papers, 2022 to 2024). Esophageal squamous cell carcinoma (ESCC) is a type of esophageal carcinoma (EC) that can affect any part of the esophagus, but is usually located in the upper or middle third. "Recently, RAD18 has been ascertained to modulate proliferation, migration, and chemosensitivity of multiple cancers, including rectal cancer and esophageal squamous cell carcinoma." (PMID 38073330, 2024). "RAD18 confer esophageal squamous cell carcinoma cells radioresistance." (PMID 35426246, 2022). "For example, RAD18 is up-regulated in human esophageal squamous cell carcinoma (ESCC) and promotes invasion and migration of ESCC cells via the JNK-MMPs pathway." (PMID 38073330, 2024).
glioblastoma (2 papers, 2022 to 2024). The most malignant astrocytic tumor (WHO grade IV). "Comparing the overall survival of patients suffering from glioblastoma with high RAD18 expression to the ones with low RAD18 expression showed that the group with high levels had a significantly decreased overall survival compared to the low expressors." (PMID 35365623, 2022). "Therefore, the relationship between RAD18, DNA damage tolerance, the hypermutator phenotype, and clinical outcome must be clarified using in vivo models in order to validate the RAD18 signaling axis as a therapeutic target in glioblastoma." (PMID 38438348, 2024). "Therefore, RAD18 expression correlates with the survival of glioblastoma patients and this supports the hypothesis that RAD18 protects glioblastoma cells against the current therapy options." (PMID 35365623, 2022).
pancreatic adenocarcinoma (2 papers, 2021 to 2026). "Here, we employed WGCNA to identify novel hub genes including PKMYT1, WDHD1, ASF1B, and RAD18, and proposed for the first time their oncogenic roles during pancreatic adenocarcinoma progression." (PMID 35047023, 2021).
rectal cancer (2 papers, 2019 to 2024). A primary or metastatic malignant neoplasm that affects the rectum. "Taken together, these consequences implied that downregulation of RAD18 enhanced the chemoradiosensitivity of rectal cancer cells in vivo through activating the caspase‐9‐caspase‐3‐related apoptotic pathway." (PMID 31033216, 2019). "Colony formation assay was used to reveal the character of RAD18 in resistance to irradiation in rectal cancer cell lines." (PMID 31033216, 2019). "To validate the function of RAD18 in resistance to 5‐Fu, we detected the survival rate of rectal cancer cells exposed to different doses of 5‐Fu by CCK‐8 proliferation assay." (PMID 31033216, 2019). "In summary, these results revealed that knockdown of RAD18 markedly improved the sensitivity of rectal cancer cells to chemotherapy, radiotherapy, and concurrent chemoradiotherapy." (PMID 31033216, 2019). "As predicted, depletion of RAD18 in rectal cancer cell lines led to the accumulation of chemoradiation‐induced genomic damage and promoted cell apoptosis significantly, whereas the DNA damage sites and cell apoptosis in control group were relatively few." (PMID 31033216, 2019). "Further, we explore the relationship between RAD18 expression in rectal cancer cell lines and concurrent chemoradiation sensitivity." (PMID 31033216, 2019). "Inhibition of RAD18 expression in rectal cancer cells pronouncedly attenuated the proliferation and promoted apoptosis after exposing to irradiation or/and 5‐fluorouracil (5‐Fu)." (PMID 31033216, 2019). "It seemed that inhibition of RAD18 level functioned as an accelerator promoting the activation of caspase‐9‐caspase‐3‐dependent apoptotic signaling responding to chemoradiation, thus effectively facilitated the apoptosis of rectal cancer cells." (PMID 31033216, 2019). "For further study, we evaluated whether RAD18 depletion‐induced hypersensitivity to chemoradiation was attributed to more double‐strand breaks in rectal cancer cells." (PMID 31033216, 2019). "The positive staining of RAD18 was primarily located at the nucleus of rectal cancer cell." (PMID 31033216, 2019). "RAD18 downregulation sensitized rectal cancer cells to nCRT both in vitro and in vivo." (PMID 31033216, 2019). "Therefore, RAD18 participated in mediating the response to chemoradiotherapy in rectal cancer." (PMID 31033216, 2019). "To inquire into the functional effects of RAD18 on biological behaviors of rectal cancer cell, we transfected RAD18‐targeting shRNA and control into adopted rectal cancer cells, HCT‐116, and DLD‐1 to generate specific knockdown‐RAD18 cell models." (PMID 31033216, 2019).
anaphylaxis (1 paper, 2019). An acute hypersensitivity reaction that occurs from exposure to an allergen. "This approach identified several genes that are associated with aging (ATP2B2, CAV3, CNTN3, CTNNA2, GRID2), inflammation (ATP2B2, CAV3, RAD18, KBTBD8), vascular permeability (SFXN5, RAD18) and anaphylaxis (CAV3, RAD18, CTNNA2, ATP2B2 and GRID2)." (PMID 31701027, 2019).
anemia (1 paper, 2020). A reduction in the number of red blood cells, the amount of hemoglobin, and/or the volume of packed red blood cells. "Moreover, the expression of Rad18, Fanconi anemia group D2 protein (FANCD2) and Fanconi anemia group J protein (FANCJ) proteins were also upregulated." (PMID 32365503, 2020).
bone osteosarcoma (1 paper, 2024). A usually aggressive malignant bone-forming mesenchymal neoplasm arising from the bone. "To this end, we initially depleted BRCA1 and RAD18 in human bone osteosarcoma cells (U2OS) and studied replication fork recovery by DNA fiber analysis." (PMID 38943334, 2024).
cervical squamous cell carcinoma (1 paper, 2025). A squamous cell carcinoma arising from the cervical epithelium. "We selected 6 RAD18 SNP and performed mismatch amplification PCR on 650 cases of CIN III, 580 cervical squamous cell carcinoma (CSCC), and 1320 healthy controls." (PMID 40859476, 2025). "We designed a case-control study based on a large sample population, selecting 6 SNP loci from RAD18 and detecting their distribution in the peripheral blood cell genomes of 650 cases of CIN III, 580 cases of cervical squamous cell carcinoma (CSCC), and 1320 normal healthy controls." (PMID 40859476, 2025).
diabetes (1 paper, 2023). "Furthermore, the risk of diabetes is significantly increased by polymorphisms in Rad18 and Xpd repair genes." (PMID 38001980, 2023).
eye cancers (1 paper, 2024). "Additionally, other genes such as ATR, RAD18, and FANCD2 were the most frequently mutated in specific cancer types such as skin, kidney, and eye cancers, respectively." (PMID 39421870, 2024).
lung adenocarcinoma (1 paper, 2022). A carcinoma that arises from the lung and is characterized by the presence of malignant glandular epithelial cells. "Consistent with the results in databases, we found that the expression of REV1, Rad18 and RPA32 was dramatically upregulated in lung adenocarcinoma tissues, as shown by immunohistochemical (IHC) staining of 5 pairs of lung adenocarcinoma and adjacent tissues." (PMID 35115490, 2022). "The GEPIA database prediction results showed positive correlations between the expression of Rad18, PCNA, RPA32 and that of SERTAD2 in lung adenocarcinoma; indeed, the correlation between Rad18 and SERTAD2 was the most significant (R = 0.46, P < 0.0001)." (PMID 35115490, 2022).
lymph node metastasis (1 paper, 2025). "Clinical data analysis further showed that the polymorphisms of RAD18 rs250403 and rs615967 were significantly correlated with prognostic indicators such as family history of tumor, differentiation grade, lymph node metastasis, and vascular involvement." (PMID 40859476, 2025).
malignant peripheral nerve sheath tumor (1 paper, 2018). Malignant peripheral nerve sheath tumor (MPNST) is a rare and often aggressive soft tissue sarcoma occurring in a wide range of anatomical sites. "For instance, 11% of renal cell carcinoma (RCC) and 5% of pancreatic tumors have inactivating RAD18-deletions and 7% of malignant peripheral nerve sheath tumors lack RAD6B." (PMID 29721165, 2018).
melanoma (1 paper, 2022). A malignant, usually aggressive tumor composed of atypical, neoplastic melanocytes. "For example, RAD18 promotes cell proliferation in melanoma, and its elevated expression is correlated with patients' unfavorable survival." (PMID 35426246, 2022).
metastatic tumor (1 paper, 2024). "The RAD18 IHC scores were significantly higher in the BRCA1-mutated primary and metastatic tumor samples, relative to WT tumors." (PMID 38943334, 2024).
Nijmegen breakage syndrome (1 paper, 2017). Nijmegen breakage syndrome is a rare genetic disease presenting at birth with microcephaly, dysmorphic facial features, becoming more noticeable with age, growth delay, and later-onset complications such as malignancies and infections. "NBS1 (mutated in Nijmegen Breakage Syndrome) interacts with Rad18 at the Rad6-interacting domain to help recruit Rad18 to damaged DNA." (PMID 28208741, 2017).
prostate carcinoma (1 paper, 2024). A carcinoma that arises from epithelial cells of the prostate gland. "Thus, in the meta-analyses of prostate cancer, we explored two top gene sets whose GSAS were driven by ESM1, and by SMC6, CDT1 and RAD18." (PMID 38597610, 2024).
prostate tumors (1 paper, 2024). "We propose that future studies should explore this RAD18/UBC13/PALB2/RNF168 fork recovery pathway in additional models of BRCA1-deficient cancers, including breast and prostate tumors." (PMID 38943334, 2024).
sarcoma (1 paper, 2022). A usually aggressive malignant neoplasm of the soft tissue or bone. "On the other hand, we found that Rad18 was significantly overexpressed in multiple types of cancers and associated with a poor prognosis of patients with sarcoma." (PMID 35459258, 2022).
squamous intraepithelial lesions (1 paper, 2020). "Although increased abundance was seen for each protein, composite scores only identified significant increases in RAD18 and RPA70 levels between NED and high grade squamous intraepithelial lesions (HSIL)." (PMID 33374731, 2020).
cancer (43 papers, 2009 to 2026). A tumor composed of atypical neoplastic, often pleomorphic cells that invade other tissues. "RAD18, a key E3 ubiquitin ligase implicated in DNA repair and genome stability, is tightly linked to cancer malignant progression, yet its pan-cancer prognostic and immunotherapeutic value remains poorly defined." (PMID 42115304, 2026). "RAD18 was significantly overexpressed in 22 cancer types, associated with gene mutation, hypomethylation, poor prognosis and favorable diagnostic efficacy, serving as an independent poor prognostic factor for multiple cancers." (PMID 42115304, 2026). "Except for these three genes, two genes, RAD18 and sMARCA5, linked to tumor progression and poor prognosis in several cancers were poorly studied in HCC." (PMID 39865406, 2025). "Recent studies suggested that RAD18 loss in BRCA1-deficient cancer cells reduces cell survival because of the role of RAD18 in ssDNA gap filling in these cells." (PMID 38943334, 2024). "As germline mutations in genes involved in HR repair are relatively common in cancer patients, we decided to exploit data for RAD18 germline variants identified in cancer patients by the CZECANCA consortium." (PMID 38884202, 2024). "We also performed functional analysis of a panel of cancer-related RAD18 variants and identified several mutations with abrogated IR-induced foci accumulation and 53BP1 -inhibitory activity." (PMID 38884202, 2024). "Based on the important function of the UBZ domain, we focused on examination of RAD18 variants identified in Czech cancer patients that showed impaired accumulation to IR-induced foci." (PMID 38884202, 2024). "RAD18 has been identified to be an oncogene in malignant tumors and is linked with cancer metastasis." (PMID 38073330, 2024). "The prevalence of truncating or functionally-impaired RAD18 germline variants was too low in our dataset of the cancer patients and controls to evaluate their association with the risk of individual cancer diagnoses." (PMID 38884202, 2024). "Owing to its pivotal role in error-prone DNA synthesis, RAD18-mediated TLS has the potential to contribute to the mutational burden of cancer genomes." (PMID 27377895, 2016). "Elevated RAD18 expression has been linked to reduced 5-year survival rates in cancer patients." (PMID 40016217, 2025). "Overall, we identified six protein-truncating germline variants in 13 (0.07%) of the 17 654 cancer patients analyzed, indicating that germline, protein-truncating RAD18 variants are rare, preventing assessment of their potential impact on the cancer risk in our dataset." (PMID 38884202, 2024). "Combined defects in translesion DNA synthesis, DNA gap filling and DSB repair caused by the loss of RAD18 function may contribute to genome instability in cancer cells." (PMID 38884202, 2024). "We also provide preliminary evidence for the potential clinical relevance of this novel fork recovery pathway in BRCA1-mutated cancers, as RAD18 is over-expressed in BRCA1-deficient cancers, and RAD18 loss compromises cell viability in BRCA1-deficient cancer cells." (PMID 38943334, 2024). "Moreover, there is growing evidence that deregulation of the RAD18 function shapes the mutational landscape of the cancer cells." (PMID 38884202, 2024). "Indeed, multiple reports connect RAD18 and downstream TLS factors to tolerance of oncogene-induced replication stress, overexpression of RAD18 is also associated with increased survival, chemoresistance and cancer progression in various types of cancer." (PMID 36480547, 2022). "Based on this association, RAD18 overexpression may not only impact cancer cell stemness, but also extend to play a role in the TME." (PMID 35413945, 2022). "Finally, we identified several new loss-of-function mutations in RAD18 in cancer patients suggesting that RAD18 could be involved in cancer development." (PMID 38884202, 2024).